IL6 (interleukin 6)
Diseases named in the same sentence as IL6 in open-access papers (continued):
Sharing a sentence is not in itself a finding about the gene and the disease.
lung carcinoma (continued). "Stimulation with GM-CSF enhanced expression of mRNA coding of TNF-α, IL-1, and IL-6 in AMs and monocytes from patients with lung cancer in a time-dependent manner and isolation of AMs from patients with lung cancer receiving GM-CSF therapy and cultured with LPS showed enhanced IL-6 secretion." (PMID 26316944, 2014). "Elevated levels of procoagulant factors, such as lupus anticoagulant, anticardiolipin antibodies to factor VIII, and certain cytokines such as interleukin-6 and tumor necrosis factor, have also been identified as increased risk factors for VTE in patients with lung cancer." (PMID 24574864, 2014). "Consistent with our hypothesis, our data revealed that 5 mmol/L (p<0.05) or 10 mmol/L (p<0.005) metformin could significantly reduce lung cancer cell invasion, which was induced by IL-6 in both A549 and HCC827 cell lines." (PMID 24789104, 2014). "Interestingly, co-culturing lung cancer cells with macrophages resulted in increases of IL-1β and IL-6, which, in turn, stimulate lung cancer cells to induce SAA1/2 production." (PMID 28250368, 2014). "Therefore, preceding our planned clinical trial of tocilizumab, we designed the two studies described here to evaluate the levels of IL-6 in patients with lung cancer and the effect of tocilizumab in a murine model of human cancer cachexia." (PMID 25010770, 2014). "Upon LPS stimulation, IL-6 secretion was increased by AMs from patients with lung cancer." (PMID 26316944, 2014). "We previously reported the role of IL-6 in a murine model of cancer cachexia and currently documented a patient in whom tocilizumab, anti-IL-6 receptor antibody, dramatically improved cachexia induced by IL-6 over-expressing lung cancer." (PMID 25010770, 2014). "Also in a study of lung cancer, patients with cachexia had heightened inflammatory responses manifested as increases of serum IL-6, soluble TNF-α receptor and C-reactive protein (CRP)." (PMID 25010770, 2014). "What precise roles do TGF-β, IL-6, IL-17, and IL-22 play in lung cancer immunopathology?" (PMID 24872958, 2014). "The involvement of inflammation in tumorigenesis, progression, and metastasis is widely accepted; however, whether IL-6-targeted therapies will prolong the survival time of lung cancer patients remains uncertain." (PMID 24260500, 2013). "Our previous studies suggested that HPV may be involved in lung cancer development through up-regulating the expressions of IL-6, IL-17 and the anti-apoptotic Mcl-1, and result in promotion of cancer cell growth." (PMID 23349885, 2013). "G-CSF- and IL-6-producing lung cancer is comparatively rare because we could find only 5 reports concerning G-CSF- and IL-6-producing lung cancer in PubMed." (PMID 23710188, 2013). "IL-6-mediated inflammation correlates with debilitating cancer-related symptoms such as fatigue, thromboembolism, cachexia, and anemia, and IL-6 signaling activation correlates with lung cancer chemotherapy resistance." (PMID 24260500, 2013). "Furthermore, TGFβ-dependent IL6 secretion has been shown to contribute to primary and acquired erlotinib resistance in lung cancer patients." (PMID 24091605, 2013). "Interestingly, this pro-inflammatory feedback loop also exists in some prostate and hepatocellular carcinomas, but only a subset of lung cancers showed increased IL6 expression." (PMID 23935876, 2013). "Likewise, several subsequent investigations demonstrated elevated serum concentrations of the hematopoietic growth factors G-CSF, granulocyte-monocyte (GM)-CSF and also interleukin-6 in patients with lung cancer and extreme neutrophilia." (PMID 22812671, 2012). "The pooled RR of lung cancer for one unit change in ln IL-6 was 1.28 (95% CI 0.92–1.79)." (PMID 22912790, 2012). "The 5 studies on IL-6 involved a total of 924 lung cancer cases." (PMID 22912790, 2012). "In addition, IL-6 was specifically increased in pleural effusions from patients with tuberculous pleurisy compared with the pleural effusions of lung cancer patients." (PMID 23028695, 2012).
lung carcinoma (continued). "After detailed studies in a large cohort, serum levels of IL-6, estradiol, and genetic polymorphisms in CYP1A1 gene may also be included as biomarkers for early detection of lung cancer." (PMID 26316937, 2012). "We had previously found IL-6 levels to be increased in MPE of patients with lung cancer." (PMID 21122157, 2010). "In a series of biochemical and genetic studies, we clearly showed that Jak2/Stat3 pathway, together with other well characterized IL-6 downstream signal pathways, regulates the autocrine production of IL-6 in lung cancer cells and various drug resistant cancer cells." (PMID 21122157, 2010). "Moreover, mutations in EGFR kinase domain have been shown to mediate STAT3 activation by IL-6 production in human lung carcinomas, suggesting that EGFR-like STAT3 activation can be mediated by IL-6R or GP130 receptors in an autocrine manner." (PMID 19088723, 2009). "For, example, some lung cancer cell lines have been shown to produce IL-6." (PMID 15570310, 2004). "Enriched tumor markers, inflammatory imbalance, particularly the IL-6/IL-10 ratio, enhanced ctDNA detection, and local immunosuppressive immune features support the utility of BALF as a minimally invasive liquid biopsy for lung cancer evaluation and risk stratification." (PMID 41970393, 2026). "Additionally, several inflammatory chemokines and interleukins (ILs), including IL-6, IL-8, and IL-10, involved in perioperative immune modulation, may help predict complications following lung cancer surgery." (PMID 41228236, 2025). "However, in both our HMEC and lung cancer studies, we found that IL-6 could directly act on the pre-neoplastic epithelial cells." (PMID 41497628, 2025). "Several studies have revealed an inverse correlation between patient survival and serum IL-6 levels or mRNA expression in various types of tumors, including head and neck squamous cell carcinoma, esophageal cancer, gastric cancer, ovarian cancer and lung cancer 9, 11, 30-32." (PMID 39781345, 2025). "Interestingly, lung cancer cells also secreted an IL-6 variant with an O-, but no N-glycan, which they state derives from defective N-glycosylation due to a reduced N-glycosyltransferase gene expression." (PMID 40663802, 2025). "TANs could produce proinflammatory factors such as monocyte chemoattractant protein-1, interleukin-8, macrophage inflammatory protein-1 alpha, interleukin-6 (IL-6), and anti-inflammatory interleukin 1 receptor antagonist (IL-1RA), thereby bolstering anti-tumor immunity in early-stage lung cancer." (PMID 38339264, 2024). "Thus, inhibiting IL-6 may be a valuable therapeutic strategy for managing osteolytic bone metastasis in lung cancer patients who smoke." (PMID 38993553, 2024). "Therefore, IL-6 plays a key role in cigarette smoke lung cancer-induced osteoclast formation." (PMID 38993553, 2024). "Thus, inhibiting IL-6 may be a valuable therapeutic strategy in managing osteolytic bone metastasis in lung cancer patients who smoke." (PMID 38993553, 2024). "Thus, the observed differences in IL-6 rs1800795 distribution among NSCLC subtypes may support the specific impact of IL-6 among lung cancer subtypes." (PMID 38103126, 2024). "KRAS-mutant lung cancer bone metastasis tissue exhibited higher p-STAT3Tyr705 levels at day 28 after intracardiac injection than at day 7, suggesting that activation of IL6/JAK/STAT3 pathway may be involved in the enhanced resistance to HOXC10 inhibition." (PMID 39191757, 2024). "Additionally, cigarette smoke lung cancer-secreted IL-6 promoted osteoclast formation." (PMID 38993553, 2024). "Furthermore, the involvement of Helicobacter pylori in lung cancer development has been observed primarily through the cytotoxicity of its main protein toxin VacA and its ability to promote the secretion of the pro-inflammatory cytokines IL-6 and IL-8." (PMID 39610830, 2024).
lung carcinoma (continued). "We in this study, for the first time, investigated the role of SIRPα in SIRPα knock‐out (KO) mice and found that lack of SIRPα significantly reduced lung cancer cell growth in mice, in association with improved MPs and neutrophils (NPs) phagocytosis and reduced IL‐6 expression in tumour tissues." (PMID 36419386, 2023). "IL-6, IL-1β, and IFN-γ had consistent associations with the lung cancer risk (HR [95% CI]: 1.31 [1.04–1.66], 1.25 [1.06–1.48], 1.23 [1.07–1.42], respectively), whereas, in ever-smokers, only IL-6 had an association with the lung cancer risk (HR [95% CI]:1.38 [1.16–1.64])." (PMID 38067398, 2023). "Statistical significance was observed for IL-1b (p = 0.044), IL-2 (p = 0.040), IL-6 (p = 0.001), IL-10 (p = 0.008), IL-12p70 (p = 0.001), and TNF-alpha (p = 0.046), indicating that these inflammatory markers are significantly associated with the risk of lung cancer." (PMID 37373957, 2023). "Additionally, we found that the levels of IL-6 were increased by 58-fold in lung cancer patients, which is also in line with previous studies that has reported a positive correlation of the increased levels of this cytokine and lymph node metastasis, distant metastasis and worse overall survival." (PMID 37580655, 2023). "In addition, a study found that during anti-CTLA4 and anti-PD-1 combination immunotherapy, a lung cancer patient developed cytokine release syndrome due to a new crown vaccination, elevated cytokine levels (IL-6, IL-10, and IFN-γ), and grade 2 liver and kidney dysfunction." (PMID 37033918, 2023). "IL-6 was associated with lung cancer risk, regardless of the histological type." (PMID 38067398, 2023). "In addition to a previous study referring to IL-6/STAT3 signaling in the activation of PDL1 expression in lung cancer and M2-type macrophages in hepatocellular carcinoma, here, we provide indirect and direct evidence for such a function of IL-6 in gastric cancer." (PMID 38001573, 2023). "IL-6 was associated with lung cancer, regardless of the histological type." (PMID 38067398, 2023). "Moreover, IL-6 silencing in human lung cancer cell lines resulted in higher DSBs after irradiation." (PMID 36547079, 2022). "To validate this hypothesis, we analyzed the expression of SMG1 and STAT3 factors by qRT-PCR in a repertoire of human tumor cell lines (29 in total, of different origins, including many lung cancer cell lines), that were selected for their positiveness for IL-6 production." (PMID 36443756, 2022). "A study of lung cancer patients undergoing radical resections demonstrated that dexmedetomidine reduced the inflammatory response and oxidative stress response, evidenced by lower IL-6, IL-8, and malondialdehyde levels, and higher superoxide dismutase levels compared to controls." (PMID 35898583, 2022). "Possible explanations for the improved prognosis echo many of the same sentiments cited in lung cancer, namely the use of BMI for patient categorization and alterations of the tumor immune microenvironment, with obese patients exhibiting higher levels of IL-6 TNF-α and c-peptide." (PMID 35326592, 2022). "We consider that a relatively lower IL-6 level (median, 4.0 pg/mL; range, 2.4–9.5 pg/mL) in our cohort, compared with patients with lung cancer and inflammatory-bowel disease, represents a stable clinical state, which may mask a potential relationship between IL-6 and REE." (PMID 35369060, 2022). "Furthermore, fibroblast growth factor receptor (FGFR) and IL-6 signaling work in a concerted manner to activate STAT3 following erlotinib treatment in EGFR-mutant lung cancer cells, contributing to the resistance of drug-treated “oncogene-addicted cancer cells”35." (PMID 35228642, 2022). "However, it has to be noted that not all PBMCs responded to S1P treatment in terms of TNF-α and IL-6 release: 85.2% (46 out of 54) of lung cancer patients responded to S1P treatment with the release of TNF-α (red slice), while 86.8% (46 out of 53) with IL-6 release (red slice)." (PMID 36010601, 2022).
lung carcinoma (continued). "Lactate is the best single biomarker in the differential diagnosis of patients with stage IIA and IIB lung cancer, with AUC = 0.726, 100.0% sensitivity, and 52.4% specificity, whereas IL-6 with AUC = 0.849 may successfully distinguish patients with stage IIB from patients with stage IIA lung cancer." (PMID 34439874, 2021). "In lung cancer, high IL-6 activity is associated with overactivated signal transducer and activator of transcription 3 (STAT3) signalling (one mechanism of TKI resistance), which can lead to IL-6 overproduction and inflammation associated with tumour resistance and development." (PMID 34834295, 2021). "The decreased levels of inflammatory factors (IL-6, IL-8, and TNF-α) strongly associated with curcumin administration (180 mg/day; ~cmax 0.5 μmol/l in human plasma) in patients with cancer, including those with lung cancer, imply a possible reduction of the M2 TAM phenotype." (PMID 34834295, 2021). "Importantly, we found that IL‐6 indeed increased TIM‐4 expression in lung cancer cell lines." (PMID 32020709, 2020). "Therefore, we concluded that TIM‐4 increased IL‐6 production in lung cancer cells." (PMID 32020709, 2020). "Therefore, the combination of IL-6 and IL-8 could be useful for evaluating the prognosis of lung cancer." (PMID 33537234, 2020). "Furthermore, we could demonstrate that specific inhibition of IL-6 trans-signaling by the sgp130Fc protein significantly ameliorated lung cancer pathogenesis." (PMID 31694340, 2019). "In addition, CCL5 and IL-6 promote Kras-dependent lung cancer cell proliferation and migration." (PMID 31316109, 2019). "However, whether miR‐206 may overcome IL6‐induced gefitinib resistance in EGFR‐mutant lung cancer remains elusive." (PMID 31507089, 2019). "Therefore, studies in which the effect of MH or its flavonoid components is tested on cancer cells in the presence of exogenous IL-6 or IL-11 could further our understanding of the molecular targets within breast and lung cancer cells." (PMID 31491838, 2019). "Importantly, both IL6 expression and ERβ expression were identified as independent prognostic factors for NSCLC, raising the possibility that IL6 and ERβ might be correlated with malignant behavior of lung cancer." (PMID 29970138, 2018). "Although clinical studies attempt with IL-6 or its receptor antibodies have had some success ameliorating lung cancer-related anemia and weight loss, these treatments could not prevent tumor expansion and its effect on muscle mass remains unknown." (PMID 30513776, 2018). "Therefore, we hypothesize that crosstalk between the E2 pathway and IL6 may play an important role in the progression of lung cancer." (PMID 29970138, 2018). "In addition, metformin can reduce IL-6-induced EMT in lung cancer patients." (PMID 30308035, 2018). "CRP and IL-6 also correlated to cytokine intensity in gastric cancer and certain clinical characteristics such as more advanced tumor stage in gastric and colorectal cancer, shorter survival in colorectal, PC and lung cancer, and cachexia in patients with colorectal, pancreatic and lung cancer." (PMID 30038723, 2018). "Given the fact that our results confirmed that ERβ promoted IL6 expression via the MAPK/ERK and PI3K/AKT signaling pathways in lung cancer cells with E2 administration, we next tested whether there exists a positive feedback loop between IL6 and ERβ in lung cancer." (PMID 29970138, 2018). "Furthermore, IL-6 mRNA-positive cancer cells were found in clinical lung cancer samples." (PMID 28951614, 2017). "Also, IL-6 was demonstrated to be activated in many human cancers, including lung cancer." (PMID 28715437, 2017). "Moreover, that we found IL-6 mRNA-positive cancer cells in KRAS mutation-negative cases suggests the potential for IL-6-targeted therapy to be applied to various types of lung cancer." (PMID 28951614, 2017).
lung carcinoma (continued). "For example, Grivennikov and Karin reported that autocrine IL-6 as an important activator of oncogenic STAT3 was implicated in lung adenocarcinomas; furthermore, SOCS3 has been found to be suppressed by hypermethylation in lung cancer cells, which promoted the progression of lung cancer." (PMID 28591704, 2017). "In addition to IL-6, we might be able to uncover other factors that are important for the tissue reconstruction ability of lung cancer stem cells by utilizing our currently established methods." (PMID 28951614, 2017). "Additionally, IL-6 and IL-8 are expressed by premalignant or senescent lung cancer cells." (PMID 29075294, 2017). "Besides the IL-6 role in regulating the growth of lung cancer cells or CSCs, the IL-6 role in controlling the epithelial-mesenchymal transition (EMT) process has also been suggested, and the role of IL-6 in regulating the EMT process in CSCs has never been addressed." (PMID 26675547, 2016). "Moreover, anti-IL-6 therapies have shown promise in human lung cancer cachexia." (PMID 28149280, 2016). "Thus, the high phosphorylation level of ATM contributing to IL-6 correlated lung cancer metastasis indicates that the functions of ATM might be dependent on cell stress, DNA damage and signaling networks." (PMID 26528698, 2015). "Though activating mutations in epidermal growth factor receptor (EGFR) resultes in activate transcription of IL-6, and activated Ras may also lead to IL-6 induction in lung cancer cells, the comprehensive mechanisms for IL-6 production in lung cancer cells remain unclear." (PMID 25504436, 2015). "Third, we only assessed one polymorphism in the IL-6 gene, therefore, we can not rule out the possibility that other polymorphisms or haplotypes in this gene might be implicated in the development of lung cancer." (PMID 24984610, 2014). "Also they suggested that IL-6 could be used as a prognostic marker for lung cancer survival among those patients who have received chemotherapy." (PMID 26316944, 2014). "Cigarette smoking is a most important risk factor for lung cancer, and it may modify the association between IL-6 rs1800796 polymorphism and risk of lung cancer, the subgroup analysis stratified by smoking status (no vs. yes) was performed." (PMID 24984610, 2014). "It was suggested that targeting IL-6 could potentially improve lung cancer therapeutic techniques." (PMID 26316944, 2014). "If the serum G-CSF and IL-6 level are measured commonly in lung cancer presenting with elevated white blood cell counts and C-reactive protein level, the more G-CSF and IL-6-producing lung cancer could be found." (PMID 23710188, 2013). "And we found no clear support for an overall relationship between IL-6 and lung cancer risk." (PMID 22912790, 2012). "Therefore, CYP1A1 activation might be the reason for the reduced estradiol and thereby increased expression of IL-6 in lung cancer." (PMID 26316937, 2012). "Through the IL-6/STAT3 signalling pathway, CAFs enhance the metastatic potential of lung cancer cells, promoting angiogenesis by elevating VEGF and bFGF levels, facilitating cancer invasion and migration." (PMID 40407951, 2025). "Comparison and efficacy evaluation of IL-6 and TNF-a levels before and after chemotherapy in the two groups of patients with lung cancer." (PMID 40265008, 2025). "Clinical trials demonstrate safety and efficacy with EPA (1.6 g) + DHA (0.8 g) daily for 12 weeks in lung cancer patients, showing improved nutritional status and suppressed inflammatory markers (CRP, TNF-α, IL-6)." (PMID 40808836, 2025). "In lung cancer, CAFs are a major source of IL6 and CAF‐derived IL6 promotes metastasis via STAT3 signalling." (PMID 39743376, 2025).